MALAT1 (metastasis associated lung adenocarcinoma transcript 1)
Diseases named in the same sentence as MALAT1 in open-access papers (continued):
Sharing a sentence is not in itself a finding about the gene and the disease.
chronic rhinosinusitis (1 paper, 2022). Chronic form of sinusitis. "In support of these results, MALAT1 has been shown to exhibit a close relationship with chronic rhinosinusitis." (PMID 36149748, 2022).
cognitive decline (1 paper, 2025). "By contrast, in subacute and chronic phases, persistent autophagic stress, impaired flux, and upregulation of SASP factors and ceRNA networks (e.g., MALAT1–miR-26b, CCL3) contribute to sustained neuroinflammation and cognitive decline." (PMID 41007413, 2025).
colon adenoma (1 paper, 2023). An adenoma that arises from the colon. "Among the 30 MALAT1-targets shared by both the small intestine and colon, ZNF638 and SENP8 levels are predictive of colon adenoma patient overall survival and disease-free survival." (PMID 37325561, 2023).
colorectal adenoma (1 paper, 2022). An adenoma that arises from the colon or rectum. "Another study confirmed increased levels of MALAT1 in colorectal adenomas and a significant difference between the type and number of polyps compared to unaffected colon epithelium." (PMID 35887000, 2022). "The study provided novel insight into chromosomal rearrangements in colorectal adenomas and provided new candidate biomarker lncRNA MALAT1 for further investigation." (PMID 35887000, 2022).
coronary artery stenosis (1 paper, 2023). "The PCA revealed that the expression signatures of RMRP, MIAT, NTT and the expression profiles of MALAT1, HSPA1A, and NLRP3 moderately differed between the thallium stress test (+) CAG (–) and thallium stress test (+) CAG (+) groups regardless of significant coronary artery stenosis." (PMID 37238718, 2023).
coronary atherosclerosis (1 paper, 2022). Atherosclerosis of the coronary vasculature. "Notably, a recent study revealed that the MALAT1/miR-15b-5p/MAPK1 and mTOR signaling pathways were essential to the development of coronary atherosclerosis." (PMID 35910856, 2022).
dementia (1 paper, 2025). Loss of intellectual abilities interfering with an individual's social and occupational functions. "For example, Apoe encodes an apolipoprotein that has a well‐established role in neurodegeneration and dementia, and Malat1 codes for a long noncoding RNA that is dysregulated in immune cell subtypes in association with aging and frailty." (PMID 40371813, 2025).
dermatitis (1 paper, 2023). An inflammatory process affecting the skin. "Further results also showed that Hsa_circ_0004287 reduced the stability of MALAT1 by competitively binding to IGF2BP3 and MALAT1 in an m6A-dependent manner in 2,4-dinitrochlorobenzene- (DNCB-) induced dermatitis." (PMID 37124930, 2023).
dysplasia (1 paper, 2023). A usually neoplastic transformation of the cell, associated with altered architectural tissue patterns.
Ebola Virus Disease (1 paper, 2025). "This study identified MALAT1 and HIST1H2BC as novel diagnostic biomarkers and 27 shared differentially expressed genes (DEGs) commonto Ebola Virus Disease (EVD) and its overlapping diseases." (PMID 41393400, 2025).
endometrioid adenocarcinoma (1 paper, 2020). An adenocarcinoma characterized by the presence of malignant glandular epithelial cells resembling endometrial cells. "MALAT1 was highly upregulated in the cardiomyocytes from rats with post-MI ventricular arrhythmias, and like endometrioid adenocarcinoma, MALAT1 acts as a sponge for miR-200c in cardiomyocytes." (PMID 32241300, 2020).
erectile dysfunction (1 paper, 2024). Persistent or recurrent inability to achieve or to maintain an erection during sexual activity. "Overall, the present study demonstrated that MALAT1-overexpressing BM-MSCs effectively ameliorate DM-induced erectile dysfunction in rats." (PMID 38918809, 2024).
experimental autoimmune encephalomyelitis (1 paper, 2020). An autoimmune demyelinating disease of the central nervous system that is produced experimentally in animals by the injection of homogenized brain or spinal cord in Freund's adjuvant. "In addition, lnc-MALAT1 expression is decreased in the spinal cords of mice with experimental autoimmune encephalomyelitis, and its knockdown raises the level of inflammatory cytokines (including IL-1 and IL-6)." (PMID 33111743, 2020).
gastroparesis (1 paper, 2021). Paralysis of the muscles of the stomach wall resulting in delayed emptying of the gastric contents into the small intestine. "Finally, lncRNAs appear to modulate the onset of diabetic gastroparesis; specifically, MALAT1 was found to be over-expressed in animal models of gastroparesis and in T2D patients suffering from gastroparesis-related symptoms, and its effect may be linked to smooth muscle cells." (PMID 34299336, 2021).
Hepatitis (1 paper, 2017). Inflammation of the liver. "The expression levels of HULC and MALAT1 were shown to be significantly higher in the normal background tissue of HCC than those in the normal liver tissue of metastatic liver tumor without hepatitis (HULC: fold change 14.9, P = 1.7e-06; MALAT1: fold change 17.5, P = 1.2e-06." (PMID 29170515, 2017).
Huntington disease (1 paper, 2018). Huntington disease (HD) is a rare neurodegenerative disorder of the central nervous system characterized by unwanted choreatic movements, behavioral and psychiatric disturbances and dementia. "Some lncRNAs, including myocardial infarction associated transcript (MIAT), metastasis-associated lung adenocarcinoma transcript 1 (MALAT1), and nuclear enriched abundant transcript 1 (NEAT1), influence neurodegenerative diseases such as Huntington’s disease and AD." (PMID 30469430, 2018).
ischemic disease (1 paper, 2020). Lack of blood supply to an area of the body, resulting in impairment of tissue oxygenation. "lncRNA MALAT1 expression can be induced by swimming via inhibition of apoptotic functions, thereby protecting hippocampal neurons against ischemic diseases." (PMID 32210839, 2020). "It was initially reported that genetic deletion or pharmacological inhibition of MALAT1 reduced vascular growth in vivo, suggesting that MALAT1 promoted angiogenesis in ischemic diseases." (PMID 32210839, 2020).
Kaposi's sarcoma (1 paper, 2021). A malignant neoplasm characterized by a vascular proliferation which usually contains blunt endothelial cells. "Of note, our bioinformatics analysis also demonstrated that Anril, Hotair, Malat1, Kcnq1ot1, and Meg3 regulate genes from the Kaposi sarcoma-associated herpes virus infection (KSHV) pathway." (PMID 33815273, 2021).
kidney failure (1 paper, 2025). An acute or chronic condition that is characterized by the inability of the kidneys to adequately filter the blood. "Furthermore, patients with kidney failure had an insignificantly lower expression of both MALAT1 (median: 0.32 vs. 0.40; p = 0.567) and NEAT1 (median: 0.34 vs. 0.40; p = 0.344)." (PMID 40150019, 2025).
lentivirus infection (1 paper, 2019). Virus diseases caused by the Lentivirus genus. "ASMCs were isolated from SHRs and infected with lentivirus over-expressing or silencing lncRNA MALAT1 and the expression of lncRNA MALAT1 after lentivirus infection was detected using reverse transcription quantitative polymerase chain reaction (RT-qPCR)." (PMID 31619581, 2019).
Listeria monocytogenes infection (1 paper, 2023). "Accordingly, Malat1 mutation diminished memory cell persistence in mice following LCMV Armstrong and Listeria monocytogenes infection." (PMID 38127070, 2023).
liver dysfunction (1 paper, 2023). "We found that MALAT1 deficiency significantly reduced the CLP-augmented plasma levels of AST and ALT, indicating recovery of liver dysfunction." (PMID 37398640, 2023).
lobular breast cancer (1 paper, 2010). "MALAT1 has been recently pointed as a biomarker in primary human lobular breast cancer as a result of an analysis of over 132,000 Roche 454 high-confidence deep sequencing reads." (PMID 20805891, 2010).
malnutrition (1 paper, 2025). Inadequate nutrition resulting from poor diet, malabsorption, or abnormal nutrient distribution. "Additionally, low MALAT1 expression was linked to nearly a 10-fold higher probability of severe malnutrition, as defined by the SGA (OR = 9.75; p < 0.001)." (PMID 40150019, 2025). "The multivariable analysis revealed a significantly higher likelihood of grade 3 RIOM in patients undergoing RT (OR = 4.26; p = 0.041), those with lower MALAT1 expression (OR = 5.19; p = 0.021), and those with severe malnutrition according to the SGA (SGA-C) (OR = 3.46; p = 0.043)." (PMID 40150019, 2025). "Additionally, LC patients with low MALAT1 expression had a significantly higher chance of developing severe malnutrition (p < 0.001), while those with low NEAT1 expression had an increased risk of moderate and severe malnutrition (p = 0.002)." (PMID 40150019, 2025). "Furthermore, patients undergoing RT (OR = 4.95; p = 0.017), those with severe malnutrition according to the SGA (SGA-C) (OR = 6.25; p = 0.046), and those with decreased MALAT1 levels (OR = 4.28; p = 0.025) had a significantly higher chance of losing 10% of their body weight." (PMID 40150019, 2025).
mature T cell lymphoma (1 paper, 2017). "High expression of MALAT1 as well as BMI1 was related to poor prognosis in patients with mature T cell lymphoma." (PMID 28412742, 2017).
medullary thyroid carcinomas (1 paper, 2022). "Further studies have also reported the oncogenic role of MALAT1 in medullary thyroid carcinomas (MTCs)." (PMID 35804851, 2022).
medulloblastoma (1 paper, 2021). A malignant, invasive embryonal neoplasm arising from the cerebellum. "To ascertain the role of these deregulated lncRNAs in the radiosensitivity of medulloblastoma cells, we knocked down RBM5-AS1, DANCR, and MALAT1 and overexpressed XIST in DAOY cells." (PMID 34225779, 2021).
mesenchymal tumors (1 paper, 2024). "This class of mesenchymal tumors comprises a wide array of molecular alterations, with the most common being GLI1::ACTB, GLI1::PTCH1 or GLI1::MALAT1." (PMID 39720383, 2024).
mood disorder (1 paper, 2025). A cognitive disorder a disturbance in which the person's mood is hypothesized to be the main underlying feature. "MALAT1 is associated with synaptic plasticity and cognitive processing, and its modulation could offer therapeutic insights into memory and learning deficits often observed in mood disorders." (PMID 40038891, 2025).
muscle atrophy (1 paper, 2025). The loss of muscle tissue due to inactivity or disease. "In addition, H19, HOTAIR, MALAT1 and PVT1 are highly expressed in the kidneys of CKD patients and are associated with muscle atrophy but do not directly mediate the pathogenesis of muscle atrophy in CKD patients." (PMID 40034097, 2025).
muscular dystrophy (1 paper, 2017). Muscular dystrophy (MD) refers to a group of more than 30 genetic diseases characterized by progressive weakness and degeneration of the skeletal muscles that control movement. "We used the mdx mouse model of muscular dystrophy to generate mdx/Malat1-KO double-KO mice." (PMID 28326190, 2017).
Mycoplasma pneumoniae pneumonia (1 paper, 2020). Interstitial pneumonia caused by extensive infection of the lungs (lung) and bronchi, particularly the lower lobes of the lungs, by mycoplasma pneumoniae in humans. "Our aim was to determine whether the long non-coding RNA (lncRNA) metastasis-associated lung adenocarcinoma transcript 1 (MALAT1) is involved in Mycoplasma pneumoniae pneumonia (MPP), and its possible mechanism of action." (PMID 33134293, 2020).
NK/T-cell lymphoma (1 paper, 2022). "Correlation between the expression of MALAT1 in NK/T-cell lymphoma and clinicopathologic variables showed that patients with high expression of MALAT1 had low OS." (PMID 35685474, 2022).
ocular toxoplasmosis (1 paper, 2019). Ocular toxoplasmosis is an infection in the eye caused by the parasite, Toxoplasm a gondii. "In our results—obtained in human retinal Müller cells, which have direct relevance to ocular toxoplasmosis—LINC01105, BANCR, MIR17HG, MIR155HG, lnc-SGK1, MEG3, KCNQ1OT1, NEAT1, NeST, and MALAT1 were the most dysregulated lncRNAs with known immunologic activities." (PMID 31547203, 2019).
Optic neuropathy (1 paper, 2021). "MALAT1, which is disorderly expressed in the growth, invasion, migration and cancer cell apoptosis, was shown to be associated with normal‐tension glaucoma (NTG), a type of optic neuropathy." (PMID 34599867, 2021).
ovarian disease (1 paper, 2021). "Metastasis-associated lung adenocarcinoma transcript 1 (MALAT1), a known long noncoding RNA, was reported to play a crucial role in follicular growth and ovarian disease." (PMID 33681369, 2021).
pancreatic diseases (1 paper, 2021). "Additionally, exosomal lncRNA HULC, colorectal neoplasia differentially expressed (CRNDE), and metastasis-associated lung adenocarcinoma transcript 1 (MALAT-1) were proven to have potential value in discriminating PaCa from other pancreatic diseases." (PMID 34243775, 2021).
pancreatitis (1 paper, 2021). Inflammation of the pancreas. "Existing research reveals that aberrant expression of MALAT1 plays a critical role in the occurrence of pancreatitis." (PMID 34448533, 2021).
panic disorder (1 paper, 2023). An anxiety disorder characterized by multiple unexpected panic attacks with persistent concern of recurring attacks. "Regarding panic disorder, data from our study indicates that the levels of DISC2, PANDA, HOTAIR, MALAT1 and GAS5 lncRNAs are over-expressed in the T1 patient group, while the T2 patients show similar levels to the controls." (PMID 37761918, 2023). "Further novelty concerns the gene expression levels of ncRNAs in Panic Disorder patients: from our observations, it was found that the ncRNAs DISC2, GAS5, HOTAIR, MALAT1, PANDA and miR-221-5p are significantly over-expressed in the T1 patients group compared with healthy controls." (PMID 37761918, 2023).
Parkinson’s (1 paper, 2024). "This literature highlighted the available data about the underlying cause of the incidence difference of PD in males versus females, the contribution of MALAT1 in the pathophysiology of Parkinson’s, and the available data in the literature regarding the association between MALAT1 and estrogen." (PMID 39768369, 2024).
Pca (1 paper, 2022). "We previously reported that the long noncoding RNA MALAT1, which is involved in cancer progression and metastasization, is efficiently targeted by specific gapmers in Pca cell lines and an ex vivo model of organotypic slice cultures (OSCs) derived from Pca surgery tissue explants." (PMID 35740569, 2022). "This evidence adds a layer of complexity to the role of MALAT1 in cancer, particularly in hormone-driven cancers such as PCa." (PMID 35740569, 2022). "The impact of MALAT1 targeting on the metabolic function of PCa cells was analyzed by quantitative High-resolution 1H Nuclear Magnetic Resonance (NMR) spectroscopy in MALAT1-depleted vs. LACZ PCa control cells after 48 h from gapmer delivery." (PMID 35740569, 2022). "In our hands, MALAT1 was found to modulate CHKA expression, PCho, and glutathione in PCa cells, revealing a new MALAT1-dependent link between PC biosynthesis and redox balance in cancer cells." (PMID 35740569, 2022). "In our previous work, the transcriptomic analysis performed in advanced or metastatic PCa cell lines and OSCs upon MALAT1 targeting revealed CHKA among a subset of differentially-expressed genes associated with metabolic reprogramming." (PMID 35740569, 2022). "Accordingly, the NMR spectroscopy significantly altered the choline/PC metabolism, placing MALAT1 targeting as a potential therapeutic option for PCa." (PMID 35740569, 2022). "We analyzed CHKA mRNA by qPCR upon MALAT1 targeting in PCa cells, which is characterized by high dose-responsiveness to the androgen receptor (AR) and its variants." (PMID 35740569, 2022). "Consistent with the metabolites screening, CHKA, which catalyzes the conversion of choline to phosphocholine along the Kennedy pathway, emerged among the modulated genes identified in a MALAT1-dependent transcriptome analysis performed in advanced and metastatic PCa cell lines." (PMID 35740569, 2022). "This work demonstrates that AR signaling might interact with MALAT1 in PCa cells." (PMID 35740569, 2022). "Of interest, MALAT1 depletion determined a profound reprogramming of cancer cells and tumor tissue metabolism, causing a switch toward a more glycolytic phenotype, which is unusual for PCa and does not efficiently support tumor growth." (PMID 35740569, 2022). "In order to investigate the consequences of MALAT1 targeting on the expression of CHKA, we first analyzed CHKA mRNA by qPCR in five PCa cells chosen according to the differences in their level of AR expression." (PMID 35740569, 2022). "Although the role of MALAT1 on PCa metabolism has previously been reported as impacting on the TCA cycle, the results reported here suggest that MALAT1 is more profoundly interconnected with the cellular metabolism, including a negative regulatory effect on the Kennedy pathway." (PMID 35740569, 2022). "Herein, we asked whether MALAT1 targeting could have a different impact in PCa cells cultured in the presence or absence of androgen." (PMID 35740569, 2022).
periodontal disease (1 paper, 2023). "In human and murine healthy and inflamed gingival biopsies we validated antagonistic expression of MALAT1 and miR-30b, which correlates with higher M1 markers in periodontal disease signifying the functional relationship of these noncoding RNA in shaping macrophage phenotype." (PMID 37860007, 2023). "Although further studies are required to fully characterize the role of MALAT1/miR-30b axis in periodontal diseases, our findings offer concurrent targeting of different noncoding RNA classes as a novel treatment modality to control periodontal inflammation." (PMID 37860007, 2023).
pharyngeal cancer (1 paper, 2020). "To investigate the role of MALAT1 in LHSCC, we collected microarrays consisting of 24 fresh laryngeal/pharyngeal cancer tissue samples and corresponding para-cancer normal tissue samples." (PMID 31792655, 2020).
pheochromocytoma (1 paper, 2025). "MALAT1 was also proven to upregulate pro-inflammatory factors in poststroke mice, and MALAT1 knockdown partially reduced the levels of TNF-α, IL-6, and IL-1β in mouse pheochromocytoma cell lines after oxygen and glucose deprivation/reperfusion." (PMID 40869277, 2025).
placental insufficiency (1 paper, 2024). Failure of the placenta to deliver an adequate supply of nutrients and oxygen to the fetus. "Dysregulation of MALAT1 has been associated with endothelial dysfunction in conditions like pre-eclampsia, where abnormal angiogenesis and excessive coagulation contribute to placental insufficiency." (PMID 39769397, 2024). "Regulating the expression of lncRNAs involved in angiogenesis, such as MALAT1, could also enhance vascularization and reduce the risk of placental insufficiency in high-risk pregnancies." (PMID 39769397, 2024).
Pleural effusion (1 paper, 2020). The presence of an excessive amount of fluid in the pleural cavity. "SCARNA7, MALAT1, and NONHSAT017369 showed consistent results with plasma in pleural effusions compared to EGFR wild‐type, all upregulated in the EGFR mutation group." (PMID 31691525, 2020). "We observed the same trend as we did in the pleural effusions, namely, significant upregulation of SCARNA7, MALAT1, and NONHSAT017369 in the EGFR‐mutant group compared to the EGFR wild‐type group (P < 0.05)." (PMID 31691525, 2020).
polyposis (1 paper, 2023). "To determine the epithelial cell-intrinsic role of MALAT1 in polyposis, we purified and cultured colonic crypt stem cells from APCΔIEC CTL and APCΔIECMalat1−/− mice and assessed their capacity to establish colonies on Matrigel in vitro." (PMID 37325561, 2023).